GSDME (gasdermin E)
Diseases named in the same sentence as GSDME in open-access papers (continued):
Sharing a sentence is not in itself a finding about the gene and the disease.
lupus (4 papers, 2022 to 2024). "Because GSDME expression is increased in the renal tubular epithelial cells of lupus patients, it is important to know the mechanisms underlying the increase in GSDME expression." (PMID 35279675, 2022). "GSDME expression was elevated in the renal tubules of patients with systemic lupus erythematosus (SLE) and pristane-induced lupus mice." (PMID 36920176, 2023). "In lupus mice, GSDME knockout or SP600125 administration effectively ameliorated lupus-like features by inhibiting GSDME-mediated renal tubular epithelial cell pyroptosis." (PMID 35279675, 2022). "To further investigate the role of GSDME in lupus pathogenesis, we prepared GSDME−/− mice (C57BL/6-GSDMEtm1cyagen mice)." (PMID 35279675, 2022). "In line, GSDME knockout reduced pyroptosis with effective amelioration of lupus-like features." (PMID 36142364, 2022). "Importantly, lupus-prone mice that were treated with SP600125 exhibited reduced protein expression levels of GSDME and cleaved caspase-3." (PMID 35279675, 2022). "We aimed to investigate the effects of GSDME-mediated pyroptosis on disease activity in lupus mice." (PMID 35279675, 2022). "To further verify the role of GSDME in lupus, we stimulated GSDME−/− mice with pristane." (PMID 35279675, 2022). "We found that SP600125 could significantly improve the symptoms of lupus in mice by inhibiting GSDME-mediated pyroptosis in two ways." (PMID 35279675, 2022). "Interestingly, we found that the serum of lupus patients significantly enhanced the expression of GSDME and pyroptosis." (PMID 35279675, 2022). "Thus, HK2 cells were stimulated with from the sera of lupus patients, and GSDME expression was examined." (PMID 35279675, 2022). "Subsequently, it was demonstrated that the renal tubules of pristane-induced lupus mice and SLE patients could also express high levels of GSDME." (PMID 36142364, 2022). "Here, we found high levels of GSDME in kidney specimens from SLE patients and lupus-prone mice." (PMID 35279675, 2022). "In vivo, high levels of GSDME expression were observed in the renal tubules of pristane-induced lupus (PIL) mice and SLE patients." (PMID 35279675, 2022). "However, the role of GSDME-mediated pyroptosis in lupus has not been reported." (PMID 35279675, 2022).
nonsyndromic hearing loss (4 papers, 2020 to 2024). "It is well established that mis-splicing of exon 8 of the DFNA5 (GSDME) gene leads to the translation of a mutant protein that causes autosomal dominant (AD) post-lingual progressive nonsyndromic hearing loss (NSHL)." (PMID 32486382, 2020).
oral squamous cell carcinoma (4 papers, 2023 to 2025). "Indeed, decreased GSDME expression in oral squamous cell carcinoma (OSCC) is associated with poor prognosis.Thus, this evidence suggests that GSDME mediated pyroptosis plays an essential role in tumor suppression." (PMID 38799433, 2024). "Notably, studies have shown that GSDME knockout impairs the therapeutic efficacy of ceritinib in NCI-H3122 cells, whereas GSDME knockdown attenuates the antitumor effect of cisplatin in oral squamous cell carcinoma." (PMID 40256765, 2025). "In oral squamous cell carcinoma, decitabine combined with cisplatin and immune-checkpoint inhibitors can amplify the immunotherapies outcomes, and the activation of GSDME can improve the sensitivity of chemotherapeutics and activate inflammatory tumour-cell pyroptosis." (PMID 39616223, 2024).
osteosarcoma (4 papers, 2021 to 2025). A usually aggressive malignant bone-forming mesenchymal neoplasm, predominantly affecting adolescents and young adults. "In particular, the high levels of GSDME in osteosarcoma tissues were positively associated with tumor metastasis and death of patients within 3 years." (PMID 39252612, 2025). "Overall, these results indicate that α-MG tends to induce pyroptosis in osteosarcoma cells with high expression of GSDME." (PMID 39252612, 2025). "Dioscin can induce G2/M‐phase arrest and apoptosis through the JNK/p38 pathway and activate GSDME‐dependent pyroptosis in osteosarcoma." (PMID 39616223, 2024). "Meanwhile, the effect of dioscin in osteosarcoma cells is significantly reduced when GSDME knocked out by the specific siRNA (Small interfering RNA)." (PMID 34381721, 2021). "Additionally, we detected the expression levels of GSDME in different osteosarcoma cells (U2OS, HOS, and 143B) and normal osteoblast cell line MC3T3, as well as clinical osteosarcoma samples." (PMID 39252612, 2025). "Given that caspase-3 and GSDME are two key factors involved in cell pyroptosis, we propose that caspase-3 may serve as a potential co-factor of GSDME in promoting pyroptosis in osteosarcoma cells." (PMID 39252612, 2025). "The expressions of GSDME in these osteosarcoma cells are significantly higher than the control MC3T3 cells, indicating that osteosarcoma potentially comprises a cellular subset demonstrating elevated GSDME expression levels." (PMID 39252612, 2025).
pancreatic ductal adenocarcinoma (4 papers, 2023 to 2025). An infiltrating adenocarcinoma that arises from the epithelial cells of the pancreas. "In pancreatic ductal adenocarcinoma, chemotherapeutic drugs induce concurrent pyroptosis and apoptosis, and GSDME is cleaved by activated caspase-3." (PMID 39616223, 2024).
psoriasis (4 papers, 2023 to 2025). An autoimmune condition characterized by red, well-delineated plaques with silvery scales that are usually on the extensor surfaces and scalp. "Full-length Caspase-3 expression was found to be increased in the epidermis of psoriasis patients in an Egyptian cohort and GSDME-deficient mice are protected against imiquimod-induced psoriasiform disease." (PMID 40121229, 2025). "These reductions implied that specific deficiency of GSDME in keratinocytes can alleviate psoriasis-like immune microenvironment." (PMID 38429278, 2024). "Taken together, these results suggested that GSDME deficiency suppresses IMQ-induced psoriasis-like dermatitis." (PMID 38429278, 2024). "Collectively, these results indicated that caspase-3-mediated GSDME activation occurs in the epidermis of IMQ-induced psoriasis-like dermatitis." (PMID 38429278, 2024). "Single-cell RNA sequencing (scRNA-seq) from a GEO dataset revealed GSDME upregulation in keratinocytes of psoriasis patients." (PMID 38429278, 2024). "This study reported that GSDME transcriptional levels were increased in psoriasis lesional skin and positively correlated with psoriasis progression." (PMID 38429278, 2024). "By analyzing of scRNA-seq dataset GSE162183 from Gao Y’s study, GSDME levels were elevated in keratinocytes from psoriasis patients compared to healthy controls." (PMID 38429278, 2024). "GSDME knockdown keratinocytes were established to investigate the mechanism by which GSDME in keratinocytes participates in psoriasis-like inflammation." (PMID 38429278, 2024). "In conclusion, GSDME in keratinocytes contributes to the pathogenesis and progression of psoriasis, potentially in a pyroptosis-independent manner by interacting and promoting translocation of p65 and c-jun." (PMID 38429278, 2024). "For instance, GSDME mRNA levels in skin biopsies of psoriasis patients declined on Day 15 after Brodalumab biological agents, through analyzing GSE53552 from Russell’s study." (PMID 38429278, 2024). "In the imiquimod (IMQ)-induced psoriasis-like dermatitis mouse model, both full-length and cleaved forms of caspase-3 and GSDME were elevated in the epidermis." (PMID 38429278, 2024). "Consistent with prior GEO dataset analyses from psoriasis skin samples, we observed elevated GSDME protein levels in the epidermis of IMQ-treated mice through immunohistochemistry study." (PMID 38429278, 2024). "And we also observed elevated GSDME protein expression in psoriatic skin lesion from psoriasis-like dermatitis of mice." (PMID 38429278, 2024). "Considering the established role of GSDME in cell death and proliferation, we decided to investigate it as a possible element of psoriasis pathogenesis and potential future marker of psoriasis." (PMID 37681881, 2023). "The role of the cleaved Caspase-3 and GSDME to psoriasis pathogenesis merits further exploration." (PMID 40121229, 2025). "Taken together, these data suggested that pyroptosis key gene GSDME might play a crucial role in the pathogenesis and progression of psoriasis." (PMID 38429278, 2024). "To ascertain whether GSDME plays an important role in keratinocyte responses to psoriasis-like stimulation, we first detected proliferative makers including Ki-67 and 5-Ethynyl-2’-deoxyuridine (EdU)." (PMID 38429278, 2024). "Additionally, GSDME mRNA levels were positively correlated with psoriatic severity as assessed by the Psoriasis Area and Severity Index (PASI) score." (PMID 38429278, 2024). "We speculate that the role of active caspase-3 in pathogenesis of psoriasis might primarily be to initiate GSDME cleavage and activation." (PMID 38429278, 2024). "Additionally, GSDME levels correlated with both psoriasis severity and response to biologics treatments." (PMID 38429278, 2024). "Serum GSDME could be further analyzed as a potential non-invasive marker of psoriasis and an interesting target for anti-psoriatic drugs." (PMID 37681881, 2023).
psoriasis (continued). "The obtained results suggest the engagement of GSDME in psoriasis pathogenesis." (PMID 37681881, 2023). "GSDME may exert a protective influence on the metabolic complications in psoriasis which requires further studies." (PMID 37681881, 2023). "Therefore, we explored whether S100A8 and S100A9 participate in the function of GSDME in keratinocytes for promoting psoriasis-like dermatitis." (PMID 38429278, 2024). "Considering the following: GSDME is able to direct cells towards apoptosis, psoriasis is known to decrease apoptosis, and finally, GSDME expression in psoriatic lesions and concentration in serum in our study is increased, we could assume it is indeed compensatively elevated." (PMID 37681881, 2023). "Therefore, GSDME could be a multi-faceted protein, and future studies are needed to further examine its role in psoriasis." (PMID 37681881, 2023). "However, the role of GSDME in keratinocytes for pathogenesis of psoriasis remains unclear." (PMID 38429278, 2024). "Thus, we speculate that GSDME expression might serve as a biomarker for psoriasis." (PMID 38429278, 2024). "To further explore whether GSDME is activated in psoriasis, we applied imiquimod (IMQ) cream on the wide type (WT) C57BL/6 mice dorsal skin for 5 consecutive days to establish a psoriasis-like dermatitis mouse model." (PMID 38429278, 2024). "In this study, by analyzing bioinformation databases, we found that strong transcriptional level expression of GSDME is significantly more prominent in lesional skin of psoriasis than non-lesional skin of psoriasis patients and normal skin of healthy people." (PMID 38429278, 2024). "In our recent papers, we have proved that GSDMD and GSDME could be involved in the pathogenesis of psoriasis and also potentially become a novel marker of psoriasis." (PMID 38693919, 2024). "We proved that GSDME serum concentration, its expression in psoriatic plaques and even in non-lesional skin is significantly elevated in patients with psoriasis compared to controls without psoriasis." (PMID 37681881, 2023). "On the other hand, GSDME does not currently seem to be a marker of psoriasis severity." (PMID 37681881, 2023).
rheumatoid arthritis (4 papers, 2021 to 2023). A chronic, systemic autoimmune disorder characterized by inflammation in the synovial membranes and articular surfaces. "In another auto-inflammatory disease, rheumatoid arthritis, there is a positive correlation between GSDME expression and TNF-induced pyroptosis mediated by the caspase-3/GSDME pathway in patients’ monocytes." (PMID 35844522, 2022).
bladder cancer (3 papers, 2021 to 2024). "This accumulation then triggered caspase-3, resulting in GSDME cleavage and subsequent pyroptosis of bladder cancer cells." (PMID 39479459, 2024). "Therefore, this study was designed to use the DNMT inhibitor DAC to up-regulate the expression of GSDME in tumor cells, thereby enhancing the pyroptotic activity in bladder cancer cells." (PMID 40630838, 2024). "Furthermore, there was a significant up-regulation of the key pyroptosis protein GSDME in bladder cancer cells, with a marked increase in pyroptotic cell numbers." (PMID 40630838, 2024). "This could contribute to an upregulation of the key proteins of pyroptosis, caspase-3 and GSDME, in bladder cancer cells due to nano-Erda@PLT accumulation." (PMID 39479459, 2024). "Through the caspase-3/GSDME pathway, nano-Erda@PLT accumulation induced pyroptosis in bladder cancer cells, leading to the release of tumor antigens and inflammatory factors." (PMID 39479459, 2024). "In bladder cancer, we indeed found a negative correlation between the expression of GSDME and the level of gene methylation." (PMID 40630838, 2024).
breast tumors (3 papers, 2012 to 2025). "Therefore, we hypothesize that FBZ may induce pyroptosis through the caspase - 3/GSDME pathway, thereby exerting a suppressive effect on breast tumors." (PMID 40756987, 2025). "Similarly, human breast tumor cell line MDA-MB-453, which expressed a high level of GSDME, processed pyroptosis and apoptosis." (PMID 34195074, 2021).
COVID-19 (3 papers, 2022 to 2024). A disease caused by infection with severe acute respiratory syndrome coronavirus 2. "GSDME was also shown to be cleaved in PBMCs of healthy donors after treatment with a combination of TNF-α and IFNγ, two cytokines linked to COVID-19 severity, further indicating a potential role of GSDME as a backup mechanism for cell death during SARS-CoV-2 infection." (PMID 35244141, 2022).
ductal adenocarcinomas (3 papers, 2018 to 2023). "Additionally, GSDME expression was higher in lobular adenocarcinomas than in ductal adenocarcinomas." (PMID 38066523, 2023). "Moreover, expression of GSDME was higher in lobular adenocarcinomas than ductal adenocarcinomas 40, a subtype with higher malignant than the former." (PMID 35541900, 2022). "Remarkably, GSDME gene body methylation, as opposed to the promoter, exhibited an inverse correlation with the 5-year overall survival time, specifically in ductal adenocarcinomas." (PMID 38066523, 2023).
fibrosarcoma (3 papers, 2021 to 2022). A malignant mesenchymal fibroblastic neoplasm affecting the soft tissue and bone. "Intriguingly, a recent study showed that GSDME is required for the influx but not efflux of molecules using fluorescently labelled dextrans in a murine fibrosarcoma cell line, suggesting a previously unrecognised biology of GSDME pores." (PMID 35455985, 2022).
kidney damage (3 papers, 2021 to 2022). "Targeting GSDME for the treatment of nephropathy has a bright prospect in the future." (PMID 35462927, 2022). "To investigate whether pyroptosis is involved in TCE-induced kidney damage, we tested the two main executive molecules, GSDMD and GSDME." (PMID 35656289, 2022).
myocarditis (3 papers, 2025). Myocarditis is a condition that is characterized by inflammation of the heart muscle (myocardium). "Mechanically, pyroptosis-mediated by GSDME in cardiomyocytes facilitates ICIs-associated myocarditis via mediating mitochondrial damage and releasing mitochondrial DNA (mtDNA), further activating cyclic GMP-AMP synthase (cGAS)-stimulator of interferon genes (STING) signaling pathway." (PMID 41225509, 2025). "One recent study revealed that GSDME-related pyroptosis is associated with ICI-induced myocarditis." (PMID 39762211, 2025). "In ICI-induced myocarditis, hyperactivated T cells produce excessive IFN-γ, triggering caspase-3 activation in cardiomyocytes, which cleaves GSDME to execute pyroptosis via pore formation." (PMID 40832143, 2025). "First, we integrate recent findings on non-canonical pyroptosis mediated by gasdermin E (GSDME), particularly in immune checkpoint inhibitor–induced myocarditis—an emerging and clinically relevant form of inflammatory cardiotoxicity." (PMID 40832143, 2025). "Mice lacking GSDME were protected from ICI myocarditis, with less immune cell infiltration and improved survival, demonstrating a direct pathogenic role for pyroptosis in this setting." (PMID 40832143, 2025). "Recent evidence implicates pyroptosis in ICI myocarditis: a 2024 study found that gasdermin E (GSDME) –mediated pyroptosis (rather than GSDMD) is extensively activated in ICI-related myocarditis, both in a mouse model and in patient heart samples." (PMID 40832143, 2025).
oral cancer (3 papers, 2022 to 2024). "It was proved that GSDME-mediated pyroptosis induced by chemotherapy drugs played a role in anti-tumor response of oral cancer." (PMID 37221570, 2023). "A recent study on oral cancer indicated that the expression of GSDME in oral cancer mice with PTEN knockout genes was significantly increased at an early stage, thereby inhibiting tumour progression by activating the pyroptosis response." (PMID 36127676, 2022). "Furthermore, okanin reduced the expression of GSDMD and GSDME in oral cancer cells." (PMID 39335166, 2024).
pneumonia (3 papers, 2024 to 2025). An acute, acute and chronic, or chronic inflammation focally or diffusely affecting the lung parenchyma, caused by an infection in one or both of the lungs (by bacteria, viruses, fungi, or mycoplasma.). "We next examined the role of GSDME in modulating host immune response in a mouse Staphylococcus aureus, a gram-positive bacteria, induced pneumonia model." (PMID 38195694, 2024). "To confirm that the phenotype was mediated by GSDME disruption in neutrophils, we induced LPS pneumonia in Mrp8-cre(-)/Gsdmefl/fl (WT) and Mrp8-cre(+)/GsdmeΔ/Δ littermates and observed the inflammatory milieu." (PMID 38195694, 2024). "Moreover, the expression of GSDME in the pneumonia lesions of ICI-LI patients was also increased, suggesting that GSDME-mediated pyroptosis may play an important role in the pathogenesis and development of ICI-LI." (PMID 39762211, 2025).
Salmonella Infections (3 papers, 2022 to 2026). Infections with bacteria of the genus SALMONELLA. "In THP-1 cells lacking GSDMD, GSDME allows the release of IL-1β in response to nigericin, Val-boroPro, or Salmonella infection, though limited cell death was observed with endogenous GSDME expression levels in these cells." (PMID 35563804, 2022). "In contrast, during Salmonella infection, cell lysis occurred independently of both GSDMD and GSDME, suggesting the involvement of alternative lytic mechanisms." (PMID 42044191, 2026). "In THP-1 macrophages, GSDME mediates IL-1β release and limited pyroptosis in response to nigericin treatment and Salmonella infection, as well as pyroptosis in the absence of GSDMD." (PMID 37279255, 2023).
stomach adenocarcinoma (3 papers, 2020 to 2022). "A diazepin-quinazolin-amine derivative BIX-01294 enhanced GSDME-mediated pyroptosis in human gastric adenocarcinoma cell lines." (PMID 33348858, 2020).
thyroid cancer (3 papers, 2022 to 2025). "Analysis of public datasets revealed that GSDME expression is elevated in ATC tissues compared to normal thyroid tissue and other thyroid cancer subtypes." (PMID 40978473, 2025). "Relative to normal tissues, GSDME expression was higher in most cancer types; however, it was lower in bladder urothelial carcinoma (BLCA), BRCA, COAD, KICH, kidney renal clear cell carcinoma (KIRC), PRAD, thyroid carcinoma (THCA), and uterine corpus endometrial carcinoma." (PMID 36003332, 2022). "Additionally, by integrating data from ATC-containing samples in the NCBI database, we found that GSDME (DFNA5) was significantly upregulated in ATC samples compared to normal thyroid (NT) and other types of thyroid cancer, whereas GSDMD did not exhibit a consistent upregulation trend." (PMID 40978473, 2025).